LIN28B (lin-28 RNA binding posttranscriptional regulator B)
Diseases named in the same sentence as LIN28B in open-access papers (continued):
Sharing a sentence is not in itself a finding about the gene and the disease.
sarcoma (7 papers, 2013 to 2024). A usually aggressive malignant neoplasm of the soft tissue or bone. "Lin28A is associated with fibroblast and sarcoma cell reprogramming, whereas its homologue Lin28B is associated with hematopoietic cell reprogramming." (PMID 24386298, 2013). "Such evidence has been further strengthened by a series of studies supporting that the spontaneous transformation of hBMSCs can be enhanced by LIN28B expression leading to sarcoma formation in immunocompromised mice, suggesting a prognostic factor for clinic sarcoma patients." (PMID 38951845, 2024). "Our results highlight an important role for the LIN28B/LET-7 axis in human sarcoma pathogenesis and suggest that the therapeutic targeting of LIN28B may be relevant for patients with sarcoma." (PMID 31147574, 2019). "In addition, we identified LIN28B/LET-7 as a possible molecular circuit underlying the transformed phenotype of hBMSC in vitro and associated it with the poor clinical prognosis for patients with sarcoma." (PMID 31147574, 2019). "Therefore, we tested a possible role for LIN28B in doxorubicin resistance in sarcoma." (PMID 31147574, 2019). "For example, LIN28B, might be a potential oncogenic driver for sarcoma." (PMID 28404969, 2017). "Our data support the clinical relevance of LIN28B and HMGA2 as possible prognostic markers and as molecular targets for novel therapeutic approaches in sarcoma." (PMID 31147574, 2019). "Lin28b mRNA is expressed in various sarcomas but is not normally detectable in organs other than the testis." (PMID 35148224, 2022).
bladder cancer (6 papers, 2016 to 2024). "In conclusion, the results of this study show that a loss of mH2A1 contributes to the enhancement of bladder cancer tumorigenicity and stemness through regulating Lin28B/let-7 posttranscriptional gene regulatory network." (PMID 26028027, 2016). "Knocking down the expression of macroH2A1 resulted in increased expression of LIN28B and enhanced tumorigenicity, radioresistance, degeneration of reactive oxygen species (ROS), and increased sphere formation ability of bladder cancer cells." (PMID 36831493, 2023). "They include calcium channel-encoding genes, the cell fate determinant and cold-shock protein LIN28B in bladder cancer and lymphotoxin beta (LTβ) in prostate cancer." (PMID 34203934, 2021). "The results of the ChIP assays showed that mH2A1 occupancy in the promoter region of Lin28B was reduced in mH2A1-depleted bladder cancer cell lines." (PMID 26028027, 2016). "The results of the MTT and clonogenic assays indicated that overexpression of Lin28B significantly increased bladder cancer cell proliferation." (PMID 26028027, 2016). "Collectively, these results provide evidence for the role that the mH2A1/Lin28B/let-7 regulatory circuit has in the development of bladder cancer stem cell-like properties." (PMID 26028027, 2016). "We generated LD611 cells that were stably overexpressing Lin28B to examine the direct role of Lin28B in bladder cancer." (PMID 26028027, 2016). "The increased expression of Lin28B in mH2A1-depleted bladder cancer cell lines were validated by quantitative real-time PCR (qPCR) and western blot analysis." (PMID 26028027, 2016). "We found that macroH2A1 is required for the suppression of Lin28B identified as a novel downstream target of macroH2A1 in bladder cancer." (PMID 26028027, 2016). "In addition, LIN28A/LIN28B can promote bladder cancer proliferation, invasion, and metastasis by activating the transforming growth factor-β/Smad signaling pathway to drive epithelial–mesenchymal transition (EMT)." (PMID 36831493, 2023). "Our results suggest that Lin28B/let-7 pathway is tightly regulated by macroH2A1 and its cofactors, and have a pivotal role in the bladder tumor progression and the regulation of stem-like characteristics of bladder cancer cells." (PMID 26028027, 2016). "In contrast, Lin28B expression was higher in bladder cancer cells than in normal cells." (PMID 26028027, 2016). "In bladder cancer, the long non-coding RNA LINC01451 was found to bind directly LIN28A and LIN28B and thus provoked the proliferation, invasion, and metastasis of bladder cancer." (PMID 37304235, 2023). "LIN28B can also promote the expression of MYC through the LIN28B/let-7a pathway and promote the proliferation, invasion, and metastasis of bladder cancer cells." (PMID 36831493, 2023). "In preliminary studies, we found that the expression levels of the classic proto-oncogenes, IGF2BP1, MYC, LIN28B and STAT3 in bladder cancer T24 cells were higher than those in normal cells, while the expression levels of the tumor suppressor genes FTO and TIA1 were negligible in T24 cells." (PMID 35288535, 2022). "In bladder cancer, macroH2A1 suppressed the stemness-promoting gene Lin28B through reciprocal binding to the repressive histone methyltransferase EZH2 and to the promoter region of the Lin28B gene locus." (PMID 34203934, 2021).
esophageal cancer (6 papers, 2015 to 2025). A primary or metastatic malignant neoplasm involving the esophagus. "In esophageal cancer cells or cancer stem cells, metformin reversed the expression of several inflammatory genes, including IL-8, Lin28B, Let-7, IL-1α, IL-1β, IL-1, and vascular endothelial growth factor (VEGF), preventing cellular proliferation and transformation." (PMID 30765814, 2019). "Lin-28 homolog B (LIN28B), recruited by NSUN2, enhances the stability of multiple pathway-related mRNAs, impacting esophageal cancer progression." (PMID 40809690, 2025).
esophageal squamous cell carcinoma (6 papers, 2021 to 2024). Esophageal squamous cell carcinoma (ESCC) is a type of esophageal carcinoma (EC) that can affect any part of the esophagus, but is usually located in the upper or middle third. "LIN28B also has a similar structure and stabilizes growth factor receptor-bound protein 2 (GRB2) mRNA in an NSUN2-dependent manner in esophageal squamous cell carcinoma (ESCC), thus indicating that it is a potential m5C reader." (PMID 35562754, 2022). "In esophageal squamous cell carcinoma, NSUN2 and LIN28B enhance the stability of GRB2 mRNA in an m5C-dependent manner, thereby facilitating cancer emergence and progression." (PMID 36532062, 2022).
oral squamous cell carcinoma (6 papers, 2013 to 2024). "Another study found that miR-4282 impeded tumor growth in oral squamous cell carcinoma cells by targeting LIN28B and downregulating ZBTB2, suggesting its potential as a novel biomarker for OSCC." (PMID 38532994, 2024). "However, the expression pattern and oncogenic roles of LIN28B during oral squamous cell carcinoma (OSCC) development and progression has not been well established yet." (PMID 26478718, 2015).
Ewing sarcoma (5 papers, 2019 to 2024). A small round cell tumor that lacks morphologic, immunohistochemical, and electron microscopic evidence of neuroectodermal differentiation. "The most promising LIN28(A/B) inhibitor is C1632, which targets LIN28B + cell lines both by disruption of LIN28B–let-7 interaction and in Ewing sarcoma by disruption of the interaction between EWS-FLI1 mRNA and LIN28B." (PMID 38601080, 2024). "The stability of EWSR1::FLI1 mRNA in approximately 10% of Ewing sarcomas is regulated by the carcinoembryonic RNA-binding protein LIN28B." (PMID 36672331, 2023). "Concordant with our findings, interrogation of LIN28B expression in the Cancer Cell Line Encyclopedia (CCLE) database revealed upregulated expression of LIN28B in a number of Ewing’s sarcoma cell lines." (PMID 31147574, 2019). "Deletion of LIN28B led to decreased EWSR1::FLI1 expression, which affects the self-renewal and tumorigenicity of Ewing sarcoma cells." (PMID 36672331, 2023).
multiple myeloma (5 papers, 2015 to 2025). "The ribonuclease DIS3, one of the most frequently mutated genes in multiple myeloma, is an inhibitor of LIN28B through binding and degrading LIN28B mRNA." (PMID 26123544, 2015). "In hematologic malignancies cervical cancer and multiple myeloma SOX6 demonstrates tumor-suppressive properties by inhibiting proliferation, inducing cellular senescence or apoptosis, and regulating critical pathways including TGFβ2-Smad2/3 and LIN28B-MYC." (PMID 40866912, 2025).
non-small cell lung carcinoma (5 papers, 2015 to 2023). A group of at least three distinct histological types of lung cancer, including non-small cell squamous cell carcinoma, adenocarcinoma, and large cell carcinoma. "Meanwhile, miR-203 has been shown to repress its translation through LIN28B mRNA 3′ UTR binding in non-small cell lung cancer." (PMID 37370851, 2023). "In an independent study, combined reconstitution of miR-34 and let-7 reduced the expression of the tumour promoters Lin28b, c-Met and Myc and, as a consequence, tumour growth was drastically decreased in a murine model of non-small cell lung cancer (NSCLC)." (PMID 26062952, 2015). "In contrast, overexpression of TRIM71 in non-small cell lung carcinoma (NSCLC) cells, in which the LIN28B–let-7–HMGA2 pathway was conserved, decreased cancer cell phenotypes." (PMID 35806250, 2022).
oral cancer (5 papers, 2013 to 2020). "We have provided strong evidence that the functional SNP (rs221636) in LIN28B gene contributes to oral cancer susceptibility in a Chinese population." (PMID 26478718, 2015). "We found that Lin28B was associated with poor patient prognosis, so Lin28B must participate in oral cancer progression." (PMID 24386298, 2013). "We have revealed a functional single nucleotide polymorphism [variant allele (T) of rs221636] in LIN28B,which is significantly associated with oral cancer susceptibility in a Chinese population, thus supporting the key roles of LIN28B during oral tumorigenesis." (PMID 26478718, 2015). "Depletion of Lin28B attenuated carcinogen-induced proliferation, migration, and invasiveness of oral cancer cell lines in vitro, yet the downstream targets of Lin28B remain elusive." (PMID 32957697, 2020). "In the line with this, stable overexpression of Lin28B in oral cancer cells promoted cell migration, invasion, colony formation, and tumor growth in vivo." (PMID 32957697, 2020). "Accumulating evidence has revealed essential clues regarding LIN28B expression and potential roles in oral cancers." (PMID 26478718, 2015). "For example, over-expression of LIN28B in oral cancer cells promotes the expression of Survivin, an apoptosis inhibitor." (PMID 26123544, 2015). "Further studies will be performed to determine initiated Lin28B activation in oral cancers, and the related functional pathways and molecular mechanisms." (PMID 24386298, 2013). "But in consideration of the similarity of Lin28A and Lin28B, we reserved functions of both proteins in oral cancer cell malignancy." (PMID 24386298, 2013). "A recent study showed that stable expression of LIN28B in oral cancer cells promoted the expression of VEGF, suggesting that LIN28A/LIN28B may be involved in the regulation of tumor angiogenesis." (PMID 26123544, 2015). "To confirm this hypothesis, we enforced Lin28B expression in oral cancer cell lines, and then observed the in vitro and in vivo effects." (PMID 24386298, 2013). "Besides, subsequent assays tested by Lin28B (abcam) antibody in cell extracts also detected slightly higher expression of Lin28B in oral cancer cell line SCC9, SCC15, SCC25 than in normal keratinocytes, including both primary cells (OKC1 and OKC2) and cell line (HaCaT cell)." (PMID 24386298, 2013). "Taken together, these studies highlight the importance of Lin28B in OSCC metastases and establish this RBP as an important prognostic marker as well as therapeutic target in oral cancer." (PMID 32957697, 2020). "LIN28B levels in these OSCC sample can be graded as low or high expression group, while negative, low expression and high expression in normal oral mucosa samples, thus indicating that LIN28B was aberrantly overexpressed in a fraction of oral cancers." (PMID 26478718, 2015). "In addition, Lin28B protein was pronouncedly increased in oral cancer tissues compared to the pair-matched adjacent non-cancerous tissues (n = 3)." (PMID 26478718, 2015).
pancreatic ductal adenocarcinoma (5 papers, 2017 to 2023). An infiltrating adenocarcinoma that arises from the epithelial cells of the pancreas. "Here, the authors show Pancreatic ductal adenocarcinoma (PDAC) epithelial cells with high level of Lin28b secrete Wnt5a to upregulate Lin28b expression in cancer-associated fibroblasts, which in turn promote growth of PDAC cells via production of PCSK9." (PMID 37898598, 2023). "The histone deacetlylase (HDAC) sirtuin 6 (SIRT6) has been shown to act on the LIN28B locus to remove K3K9ac/56ac motifs, decreasing LIN28B expression and suppressing pancreatic ductal adenocarcinoma." (PMID 37370851, 2023).
acute myeloid leukemia (4 papers, 2017 to 2024). Acute myeloid leukemia (AML) is a group of neoplasms arising from precursor cells committed to the myeloid cell-line differentiation. "Reactivated LIN28A or LIN28B expression almost invariably correlates with poor prognosis in many tumors, including acute myeloid leukemia, brain cancers, and NB." (PMID 38732012, 2024). "While some reports relate Lin28A and its homologue Lin28B to hematopoiesis and also acute myeloid leukemia, it remains unclear if differences in blood counts are direct or indirect effects of Lin28A expression in hGFAP-positive cells." (PMID 34801069, 2021).
lung adenocarcinoma (4 papers, 2018 to 2024). A carcinoma that arises from the lung and is characterized by the presence of malignant glandular epithelial cells. "Clustered Regularly Interspaced Short Palindromic Repeats (CRISPR)/Cas9-mediated knockout of LIN28B in patient-derived lung adenocarcinoma cells dramatically attenuated proliferation, colony formation, migration, and invasion ability in vitro." (PMID 37304235, 2023). "We demonstrated that the histone acetyltransferase PCAF, via its cold shock domain, directly interacts with and subsequently acetylates Lin28B in lung adenocarcinoma-derived H1299 cells." (PMID 29301498, 2018). "In this study, we found that knockdown of Lin28B in the human lung adenocarcinoma cell line H1299 abrogated the inhibition of let-7 miRNA." (PMID 29301498, 2018).
breast tumors (3 papers, 2013 to 2024). "Limiting dilution assays confirmed the increased in vivo tumorigenic capacity of Lin28B-expressing 4TO7 tumors, suggesting that Lin28B facilitates the stem cell properties of breast tumor cells." (PMID 35173168, 2022). "The pluripotent factor Lin28B is frequently expressed in breast tumors and is particularly upregulated in the triple negative breast cancer subtype." (PMID 35173168, 2022). "Our clinical data show that higher Lin28B expression in breast tumors is correlated with lower exosomal let-7s." (PMID 35173168, 2022). "Perhaps, Lin28B can also promote breast tumor cell EMT transition like Lin28A50, a process accompanied by low proliferation." (PMID 35173168, 2022). "Until now, Lin28A and Lin28B expression has been reported distinctively or exclusively in several tumours including gastric, colorectal, gonad, hepatocellular and breast tumours distinctively or exclusively." (PMID 24386298, 2013). "For example, Lin28A was expressed in HER2-overexpressing breast tumour but Lin28B was expressed in triple-negative breast tumour." (PMID 24386298, 2013). "Furthermore, the pluripotent factor lin-28 homolog B (LIN28B) is highly expressed in breast tumors, and studies have shown that low-let-7s exosomes released by tumors are a prerequisite for LIN28B-induced immunosuppression." (PMID 38835784, 2024). "Therefore, we concluded that Lin28B promotes breast tumor distal metastasis with a major focus on the lung tissue." (PMID 35173168, 2022).
central precocious puberty (3 papers, 2011 to 2020). "LIN28B rs314280 is significantly associated with age at menarche in Asians and European women and may contribute to idiopathic central precocious puberty susceptibility in Chinese girls." (PMID 32571380, 2020).
cholangiocarcinoma (3 papers, 2022 to 2025). A carcinoma that arises from the intrahepatic biliary tree (intrahepatic cholangiocarcinoma) or from the junction, or adjacent to the junction, of the right and left hepatic ducts (hilar cholangiocarcinoma). "For example, in cholangiocarcinoma, the Lin-28 homolog B (LIN28B)/ Transforming Growth Factor Beta (TGF-β)/TGFBI feedback loop encourages cell migration and carcinogenesis." (PMID 39752341, 2025). "To further investigate the potential role of LIN28B in CCA pathogenesis, we studied the effect of LIN28B overexpression in the cholangiocyte cell line MMNK-1 and cholangiocarcinoma cell lines HuCCT-1 and KKU-214." (PMID 34548635, 2022). "Our results suggest that feedback collaboration between LIN28B and TGF-β plays a role in cholangiocarcinoma metastasis and provide a novel target for therapeutic intervention for CCA." (PMID 34548635, 2022). "Overexpression of TGFBI alone promoted cholangiocarcinoma cell migration and EMT changes, but not spheroid formation, suggesting that TGFBI partially contributes to LIN28B-mediated aggressive cell behaviour." (PMID 34548635, 2022). "In addition, LIN28B promotes migration and proliferation in cholangiocarcinoma through TGF-β-induced protein (TGFBI), although a mechanistic relationship between LIN28B and TGFBI mRNA 3′ UTR has not yet been verified." (PMID 37370851, 2023).
lymphoma (3 papers, 2011 to 2021). A malignant (clonal) proliferation of B- lymphocytes or T- lymphocytes which involves the lymph nodes, bone marrow and/or extranodal sites. "Recently, the LIN28 family member LIN28B, whose expression in highly elevated in a number of human tumors, was shown to be a direct MYC target in P493-6 B cells and mouse lymphoma." (PMID 22039435, 2011).
serous ovarian cancer (3 papers, 2018 to 2023). "It was reported that the RNA-binding protein (RBP) LIN28B bound to and stabilized NEAT1 in high-grade serous ovarian carcinoma (HGSOC)." (PMID 37986114, 2023).
triple-negative breast carcinoma (3 papers, 2015 to 2022). An invasive breast carcinoma which is negative for expression of estrogen receptor (ER), progesterone receptor (PR), and human epidermal growth factor receptor 2 (HER2). "Alternatively, the co-localization of nuclear β-catenin with intense Hmga2 staining in mouse tumors could reflect Wnt signaling enhancement of Hmga2 expression, a phenomenon observed in triple-negative breast cancer, a subtype that also tends to express high LIN28B levels." (PMID 26244988, 2015). "From all the RBPs investigated, seven were differentially expressed and upregulated (AGO2, EIF4A3, ELAVL1, IGF2BP2/3, LIN28B, and U2AF2), showing that these genes have an important role in triple-negative breast cancer development." (PMID 35805051, 2022).
colorectal tumors (2 papers, 2019 to 2023). "LIN28B/CLDN1/NOTCH3 axis positively correlates with metastatic progression of human colorectal tumors." (PMID 37318881, 2023).
diffuse intrinsic pontine glioma (2 papers, 2023 to 2024). A neuroglial tumor that arises from the middle portion of the brain stem. "Our group and others have shown that LIN28B is expressed in cell lines of diffuse intrinsic pontine glioma (DIPG), the pontine subtype of DMGs (unpublished data,)." (PMID 37370851, 2023). "Furthermore, in a paediatric brain tumour (Diffuse intrinsic pontine gliomas, DIPG), RAS signalling has recently been identified as a novel therapeutic vulnerability and the RNA-binding protein LIN28B is overexpressed in DMG and suppresses the let-7 family of microRNAs." (PMID 38637419, 2024).
fatty liver disease (2 papers, 2022 to 2024). A reversible condition wherein large vacuoles of triglyceride fat accumulate in liver cells via the process of steatosis. "While these mice developed fatty liver disease and had increased fibrogenic gene expression, there was no increase in Lin28a or Lin28b expression." (PMID 38875287, 2024).